MYO1F (myosin IF)
Description:
Myosins are actin-based motor molecules with ATPase activity. Unconventional myosins serve in intracellular movements. Their highly divergent tails are presumed to bind to membranous compartments, which would be moved relative to actin filaments (By similarity).
Tractability: Antibody: its Gene Ontology location is reachable by antibodies, with medium confidence. PROTAC: ubiquitination databases record sites on it; its protein half-life has been measured.
Gene: Protein-coding gene on chromosome 19 (8,517,463 to 8,577,464, reverse strand). Ensembl gene ENSG00000142347.
Subcellular location (Human Protein Atlas): Cytosol
Gene Ontology:
Molecular function: protein binding; protein-macromolecule adaptor activity; actin binding; actin filament binding; ATP binding; cytoskeletal motor activity
Biological process: actin filament organization; antifungal innate immune response; antiviral innate immune response; positive regulation of cGAS/STING signaling pathway; protein localization to plasma membrane; response to fungus; endocytosis; positive regulation of neutrophil chemotaxis
Cellular component: cytoplasmic side of plasma membrane; cytosol; actin cytoskeleton; microvillus; plasma membrane; unconventional myosin complex; myosin complex
Genetic constraint (gnomAD): Loss-of-function variants: 60 observed, 149.71 expected, observed/expected ratio (o/e) 0.4, 90% interval 0.32 to 0.5. The upper end of that interval is the gene's LOEUF score, 0.5, which puts it in group 2 of 6, group 1 being the genes least tolerant of losing a copy. Missense variants: 1,274 observed, 1,571.3 expected, observed/expected ratio (o/e) 0.81, 90% interval 0.77 to 0.85. Synonymous variants: 602 observed, 618.35 expected, observed/expected ratio (o/e) 0.97, 90% interval 0.91 to 1.04.
Gene-disease validity (ClinGen):
ClinGen rates the evidence that MYO1F causes each of these diseases.
nonsyndromic genetic hearing loss (autosomal dominant): Disputed. A disease characterized by hearing loss that is not part of a larger syndrome.
Homologues: Orthologues: macaque MYO1F (99% identical), pig MYO1F (96% identical), rabbit MYO1F (94% identical), dog MYO1F (94% identical), mouse Myo1f (93% identical), rat Myo1f (93% identical), guinea pig MYO1F (93% identical), chimpanzee MYO1F (90% identical), tropical clawed frog myo1f (79% identical), zebrafish myo1f (76% identical). Paralogues in human: MYO1E (72% identical), MYH7 (33% identical), MYH6 (33% identical), MYH3 (32% identical), MYH2 (32% identical), MYH8 (32% identical), MYH1 (32% identical), MYH4 (32% identical), MYH7B (32% identical), MYH13 (31% identical), MYH10 (30% identical), MYH15 (30% identical), and 32 more.